ROCK1 (Rho associated coiled-coil containing protein kinase 1)
Diseases named in the same sentence as ROCK1 in open-access papers (continued):
Sharing a sentence is not in itself a finding about the gene and the disease.
viral infection (4 papers, 2022 to 2025). "Several studies have reported that viral infections are closely associated with the activation of the RhoA/ROCK1 signaling pathway." (PMID 40142587, 2025). "Additionally, ROCK1 kinase activity can be regulated through autophosphorylation, and its aberrant activation is closely linked to cell barrier disruption, increased contractility, and abnormal vesicle transport, all of which may facilitate viral infection." (PMID 40142587, 2025). "Next, we employed two chemical inhibitors, CCG-1423 and Y27632, to further investigate the impact of the RhoA/ROCK1/MLC2 signaling pathway on viral infection." (PMID 40142587, 2025). "Notably, ROCK1’s role in viral infection likely operates through two distinct mechanisms." (PMID 40142587, 2025). "Although MVC infection activates the RhoA/ROCK1/MLC2 signaling pathway and significant effects on viral infection, our study still has some limitations." (PMID 40142587, 2025). "During the early stage of viral infection, MVC activates the RhoA/ROCK1/MLC2 signaling pathway." (PMID 40142587, 2025).
angiosarcoma (3 papers, 2013 to 2021). A malignant tumor arising from the endothelial cells of the blood vessels. "EBNA1 activating AP‐1 transcription factor pathway by binding to ATF2 and elevated expression of AP‐1 targeting VEGF; SARS and ROCK1/2 are unique regulators in angiogenesis and angiosarcoma tumour progression." (PMID 33586248, 2021). "Based on the staining performed, the expression of ROCK1 is significantly elevated in hemangioendotheliomas and angiosarcomas relative to normal endothelium." (PMID 28709411, 2017). "In the present study, we investigate the unique cellular roles of ROCK1 & 2 proteins in endothelial cells and angiosarcoma tumor progression using stably expressed short hairpin RNA (shRNA) plasmids specific for ROCK1 or ROCK2." (PMID 22934846, 2013). "Our findings revealed that ROCK1 was overexpressed in malignant vascular tumors such as hemangioendotheliomas and angiosarcomas, and ROCK2 was overexpressed in both benign and malignant vascular tumors including hemangiomas, hemangioendotheliomas, hemangiopericytomas, and angiosarcomas." (PMID 28709411, 2017).
autoimmune disease (3 papers, 2019 to 2025). A disorder resulting from loss of function or tissue destruction of an organ or multiple organs, arising from humoral or cellular immune responses of the individual to their own tissue constituents. "ROCK1 can indeed phosphorylate BACH2 in its heme-binding domain and prevent the heme-driven degradation of BACH2, thus helping protect BACH2 in settings marked by increased hemolysis, such as malaria and some autoimmune diseases." (PMID 39903532, 2025).
endometriosis (3 papers, 2020 to 2022). The growth of functional endometrial tissue in anatomic sites outside the uterine body. "Taken together, dysregulation of miR-202-3p can participate in the pathogenesis of endometriosis through influencing expression of ROCK1." (PMID 36177350, 2022). "In this research, we found that the protein expression of Rho/ROCK signalling pathway was abnormally changed in endometriosis and RhoA and ROCK1/2 were remarkably increased in eutopic and ectopic endometria." (PMID 32725958, 2020). "It is reported that RhoA, RhoC and ROCK1 were significantly higher in ectopic endometrial cells compared with the eutopic endometrial cells in endometriosis, which involved with promoted migration of endometrial cells of endometriosis." (PMID 32725958, 2020). "Further researches were performed and found that inhibition of ERK signalling by PD98059 decreased the level of activated RhoA, total RhoA, ROCK1 and ROCK2, which implied ERK pathway might involve with the regulation of RhoA/ROCK pathway in endometriosis." (PMID 32725958, 2020).
esophageal cancer (3 papers, 2020 to 2023). A primary or metastatic malignant neoplasm involving the esophagus. "Based on the data of TCGA and GEPIA, the mRNA levels of ROCK1 in esophageal cancer were higher than that in most cancers and the mRNA levels of ROCK1 in esophageal cancer were higher than that in normal tissue." (PMID 36781836, 2023).
head and neck cancer (3 papers, 2019 to 2022). A primary or metastatic malignant neoplasm affecting the head and neck. "On the other hand, miR-136-5p plays an anti-tumoral role targeting Rho Associated Coiled-Coil Containing Protein Kinase 1 (ROCK1) that attenuates Akt activation and promotes autophagy, while reducing cell migration and invasion in head and neck cancer cells." (PMID 35309939, 2022). "Moreover, miR-136-5p could enhance cisplatin sensitivity and suppress invasion and migration in head and neck cancer cells via targeting the ROCK1." (PMID 36177350, 2022).
hepatoblastoma (3 papers, 2019 to 2022). Hepatoblastoma (HB) is a malignant hepatic tumor and is the most common pediatric liver cancer. "There has been an exploration of new targets in the management of hepatoblastoma including signal transducer and activator of transcription signaling 3 (STAT3); NOTCH receptors and their ligands; PI3K/Akt, ERK and p38 signaling pathways; GPC3; PIM Kinases; ROCK1; mTOR and YAP." (PMID 31511432, 2019). "Our research further clarified the anti-tumor mechanism of lycorine, suggesting that lycorine-mediated ROCK1 activation and mitochondria-dependent apoptosis may be a novel therapeutic strategy for hepatoblastoma treatment." (PMID 31263414, 2019).
hyperlipidemia (3 papers, 2022 to 2025). "Given the portal vein hepatic first pass metabolism, the levels of D and DA prior to hydrolysis by Cyp 2C19, 3A4 and/or CES2 could be high enough to directly inhibit liver ROCK1 to contribute to the anti-hyperlipidemia activity in the different animal models and in the human trial outcome." (PMID 39779619, 2025).
infarction (3 papers, 2025 to 2026). A localised pathological necrosis of tissue resulting from obstruction of the blood supply usually by a thrombus, an embolus, or vascular torsion. "Our results indicate ROCK1 protein levels dropped, however, miR139-5p remained unaltered on day one following infarction." (PMID 40362372, 2025).
ischemia (3 papers, 2019 to 2021). A hypoperfusion of the BLOOD through an organ or tissue caused by a PATHOLOGIC CONSTRICTION or obstruction of its BLOOD VESSELS, or an absence of BLOOD CIRCULATION. "Taken together, our study demonstrated a novel lncRNA SNHG14/miR-136–5p/ROCK1 regulatory network in ischemia induce injury, providing a potential biomarker and therapeutic target for ischemia stroke." (PMID 30546117, 2019). "Further, ROCK1 expression was examined by western blot in ischemia induced cerebral injury." (PMID 30546117, 2019). "Similarly, we illustrated that ROCK1 is up-regulated in ischemia induced injury in vivo and in vitro, and preventing its expression ameliorated SNHGA14 overexpression aggravated OGD/R induced deficit and inflammation." (PMID 30546117, 2019). "Finally, we demonstrated that SNHG14 participated in regulation of inflammation induced by I/R damage via regulation of miR-136–5p/ROCK1 axis and could be a new strategy for the treatment cerebral damage induced by ischemia." (PMID 30546117, 2019).
lung adenocarcinoma (3 papers, 2022 to 2026). A carcinoma that arises from the lung and is characterized by the presence of malignant glandular epithelial cells. "MYBPH has been reported to be a transcriptional target of TTF-1 and inhibits ROCK1 activity to reduce cell motility and metastasis in lung adenocarcinoma cells." (PMID 35087137, 2022). "In this study, based on publicly available proteomic data of lung adenocarcinoma (LUAD), we used bioinformatics analysis, in vitro cellular experiments, and in vivo animal experiments to deeply investigate the functions and potential therapeutic strategies of ATOX1 and ROCK1 in LUAD." (PMID 40940984, 2025).
Lung Injury (3 papers, 2022 to 2025). "Similarly, circARHGAP5 was discovered to elevate Rock1 by sponging miR-29a-3p during nerve injury." (PMID 41327336, 2025).
medulloblastoma (3 papers, 2015 to 2021). A malignant, invasive embryonal neoplasm arising from the cerebellum. "The expression of ROCK1 was significantly higher in all four medulloblastoma subgroups compared to in adult cerebellum, but when comparing with the fetal cerebellum, only the Shh group of tumors showed a difference in the expression levels." (PMID 31888022, 2019). "The highest expression of ROCK1 was found in the Shh group while mRNA levels of ROCK2 were highest in Group 4 medulloblastomas." (PMID 31888022, 2019). "Similarly, FHOD3 promotes the occurrence of medulloblastoma by regulating RhoA/ROCK1/LIMK1 signaling." (PMID 34486491, 2021). "The expression of ROCK1 and ROCK2 showed significant differences between different molecular subgroups of medulloblastoma." (PMID 31888022, 2019). "Publicly available expression cohorts on cell lines showed mRNA expression of both ROCK1 and ROCK2 in all accessible medulloblastoma cell lines: UW228, D283, D458, D425, and DAOY." (PMID 31888022, 2019). "Expression of ROCK1 and DNMT1, two known miR-148a targets, was found to be downregulated upon miR-148a expression in medulloblastoma cells." (PMID 26097868, 2015). "Downregulation of ROCK1 and DNMT1 upon miR-148a expression is therefore likely to contribute to miR-148a's tumor-suppressive effect on medulloblastoma cells." (PMID 26097868, 2015). "Western blot analysis for ROCK1 and ROCK2 in a panel of medulloblastoma cell lines showed evident levels of protein expression from at least one of the two ROCKs in all cell lines analyzed, as well as activation of the downstream target MLC, however very low in the D458 cell line." (PMID 31888022, 2019). "In order to explore the importance of Rho/ROCK signaling in medulloblastoma, we analyzed mRNA expression levels of the downstream Rho activating kinases ROCK1 and ROCK2 in two different cohorts of medulloblastoma tissue samples, and in fetal and adult cerebellum." (PMID 31888022, 2019).
Miscarriage (3 papers, 2024 to 2025). A pregnancy that ends at a stage in which the fetus is incapable of surviving on its own, defined as the spontaneous loss of a fetus before the 22th week of pregnancy. "The reduced transcription of ROCK1 impaired trophoblast cell functions, resulting in miscarriage." (PMID 40595452, 2025). "Restoring SOX2 or ROCK1 levels mitigated these effects and reduced miscarriage rates, suggesting that migrasomes could play a key role in maintaining pregnancy." (PMID 40595452, 2025).
Parkinson disease (3 papers, 2013 to 2025). A progressive degenerative disorder of the central nervous system characterized by loss of dopamine producing neurons in the substantia nigra and the presence of Lewy bodies in the substantia nigra and locus coeruleus. "Investigations into the role of miR-361-5p in Parkinson's disease-related genes, such as ROCK1, have demonstrated a decrease in its expression." (PMID 41203125, 2025). "Using a mouse model of Parkinson’s disease, they found that ROCK-1 activates another protein previously shown to trigger the disruption of mitochondria." (PMID 31578315, 2019).
Prostatic Hyperplasia (3 papers, 2024 to 2025). "These in vivo and in vitro ROCK1 knockdown data confirmed that reduced ROCK1 signaling inhibits the recruitment and differentiation of LepR+ cells in prostatic hyperplasia." (PMID 38711089, 2024). "Moreover, MicroRNA-340 inhibits epithelial-mesenchymal transition by impairing the ROCK-1-dependent Wnt/β-catenin signaling pathway in epithelial cells derived from human benign prostatic hyperplasia." (PMID 39703506, 2024).
renal carcinoma (3 papers, 2011 to 2023). A carcinoma arising from the epithelium of the renal parenchyma or the renal pelvis. "We also investigated the relationship between miR-584 and ROCK-1 expression levels in renal cancer tissues (n=14)." (PMID 21119662, 2011).
thyroid cancer (3 papers, 2017 to 2022). "Correlation analysis revealed that the protein expression of ROCK1 was significantly negatively correlated with miR-154-3p (r = −0.350; P = 0.005) and miR-487-3p (r = −0.338; P = 0.007) expression in thyroid cancer tissues." (PMID 31820783, 2020). "For example, oncogene ROCK1 can be suppressed by miR-584 to block migration and invasion in thyroid carcinoma." (PMID 31820783, 2020). "IHC staining results also exhibited that ROCK1 protein expression was significantly elevated in thyroid cancer tissues compared with adjacent non-tumor tissues." (PMID 31820783, 2020).
acute graft versus host disease (2 papers, 2024 to 2025). A syndrome of immunologically mediated tissue damage that may occur following an allogeneic transplant, usually affecting the skin, liver, and GI tract. "Rho-associated coiled-coil containing protein kinase 1(ROCK1) is significantly upregulated in steroid-refractory acute GVHD (SR-aGVHD) patients." (PMID 40943537, 2025).
age (2 papers, 2019 to 2020). A temporal measurement of the time period elapsed since an identifiable point in the life cycle of an organism. "The ROCK1 protein level increased in the lens epithelial cells from age-related cataract patients and the old mice, respectively." (PMID 33297931, 2020).
amyloid (2 papers, 2016 to 2019). "To explore the reason of ROCK1 activation, we found that in the brain of AD patients, ROCK1 mRNA was positively correlated with amyloid pathology‐associated CERAD scores, and the results obtained are consistent with previous observation." (PMID 31287605, 2019). "To explore the mechanism of ROCK1 activation, we found that ROCK1 mRNA in the AD brain was positively correlated with amyloid pathology‐associated CERAD scores, and proposed that dysregulated transcription of ROCK1 may be associated with its activation." (PMID 31287605, 2019). "Moreover, blockade of APP Ser655 phosphorylation, or inhibition of ROCK1 activity with either shRNA knockdown or Y‐27632, ameliorated amyloid pathology and improved learning and memory in APP/PS1 mice." (PMID 31287605, 2019). "Since ROCK1 inhibition reduced BACE1‐derived β‐CTF, it is concluded that β‐CTF decrease is the key contributor preventing amyloid formation and involved in ameliorating cognitive deficits in Y‐27632‐treated APP/PS1 mice." (PMID 31287605, 2019). "Furthermore, we confirmed the molecular mechanisms for it and ROCK1 inhibition decreased amyloid plaque formation in the brain of APP/PS1 mice and prevented APP‐CTF aggregation in the surrounding halo of amyloid plaques." (PMID 31287605, 2019).
autoimmune myocarditis (2 papers, 2020 to 2024). Autoimmune myocarditis is an autoimmune disease that affects the heart. "In this study, we also addressed their contribution also to the development of autoimmune myocarditis and found that Rock1+/− and Rock2+/− developed unaffected CD4+ T cell-mediated cardiac inflammation." (PMID 32178482, 2020). "In this study, using wild-type, Rock1+/− and Rock2+/− haploinsufficient mice and mouse model of experimental autoimmune myocarditis (EAM) we addressed the role of ROCK1 and ROCK2 in development of myocarditis and postinflammatory fibrosis." (PMID 32178482, 2020). "However, neither ROCK1 nor ROCK2 participated in the progression of fibrosis in the experimental autoimmune myocarditis mouse model study." (PMID 39455522, 2024).
Autoimmunity (2 papers, 2021 to 2025). The occurrence of an immune reaction against the organism's own cells or tissues. "Employment of ROCK1 to dynamically adapt the molecular machinery of B cells to withstand pathogen-associated and environmental stressors could thus have broad relevance for infections, vaccine development, autoimmunity, and even malignancies." (PMID 39903532, 2025).
brain tumor (2 papers, 2011 to 2016). "The overexpression of ROCK-1, which is induced by activated RhoA, is related to brain tumor metastasis." (PMID 26715733, 2016).
cataract (2 papers, 2020 to 2021). Partial or complete opacity of the crystalline lens of one or both eyes that decreases visual acuity and eventually results in blindness. "Moreover, western blotting indicated that ROCK1 expression was increased in the LECs of cataract patients." (PMID 33297931, 2020).
cervical squamous cell carcinoma (2 papers, 2019 to 2020). A squamous cell carcinoma arising from the cervical epithelium. "In cervical squamous cell carcinoma, HAND2-AS1 inhibits proliferation, migration and invasion abilities in both human papillomavirus (HPV)-positive and negative cells via downregulation of Rho-associated protein kinase 1 (ROCK1)." (PMID 31889905, 2019).
cognitive decline (2 papers, 2024 to 2025). "In summary, Lingo1 upregulation in hippocampal neurons might promote myelination inhibition or myelin sheath loss through the RhoA/ROCK1 pathway, which plays important roles in the occurrence and development of postoperative cognitive decline." (PMID 39781463, 2025). "After confirming the critical roles of ROCK1 in lysosomal biogenesis and function, we further explored the effect of ROCK1 manipulation on AD pathology and cognitive decline." (PMID 39497162, 2024). "Taken together, our results demonstrated that ROCK1 knockdown prevented cognitive decline in APP/PS1 mice." (PMID 39497162, 2024). "Moreover, upregulated Lingo1 in hippocampal neurons contributed to cognitive decline after surgery through activating the RhoA/ROCK1 signaling pathway and inhibiting the EGFR/PI3K/Akt signaling pathway." (PMID 39781463, 2025).
cytomegalovirus infection (2 papers, 2015 to 2021). A herpesvirus infection caused by Cytomegalovirus. "Interestingly, the homologue of LET-502, the Rho-associated coiled-coil kinase, ROCK1, was recently shown to concentrate in the nucleolus during human cytomegalovirus infection." (PMID 34166401, 2021). "We also reveal that few cytosolic proteins including ROCK1, a key regulator of actin cytoskeleton, are degraded during HCMV infection." (PMID 26599541, 2015). "We conducted simultaneous real-time PCR and western blot analysis on cell extracts along HCMV infection and could confirm profiles that suggest active degradation of ROCK1 and ERC1." (PMID 26599541, 2015). "Interestingly, these structures were shown to be modulated during HCMV infection and the possible role of ROCK1 in modulation of these processes could be studied." (PMID 26599541, 2015).
depression (2 papers, 2019 to 2023). "Although ROCK2 is preferentially expressed in the brain, whereas ROCK1 is primarily expressed in the non-neuronal organs, a role for ROCK1 in depression cannot be completely ruled out." (PMID 31068571, 2019).
dilated cardiomyopathy (2 papers, 2020 to 2021). Cardiomyopathy which is characterized by dilation and contractile dysfunction of the left and right ventricles. "The role of ROCK1 signaling was also analyzed in Gαq-overexpressing mice (a model for dilated cardiomyopathy) crossbreed with ROCK1-knockout mice." (PMID 33906663, 2021).
erectile dysfunction (2 papers, 2009 to 2021). Persistent or recurrent inability to achieve or to maintain an erection during sexual activity. "Our previous work verified that KLK1 ameliorated corporal fibrosis via suppressing TGF-β1 and RhoA/ROCK1 pathway in aging-related erectile dysfunction." (PMID 34007408, 2021).
gall bladder cancer (2 papers, 2019 to 2022). "CircHIPK3 was found to facilitate gallbladder cancer cell proliferation via inhibiting the activity of miR-124 and enhancing rho-associated protein kinase 1(ROCK1) and cyclin dependent kinase 6 (CDK6) expression." (PMID 36606192, 2022).
genitourinary cancers (2 papers, 2022 to 2023). "In summary, we have provided data demonstrating that Sirt6 suppression promotes mitochondrial fission by activating the ROCK1‐Drp1 signalling pathway, thus inducing kidney injury." (PMID 35842903, 2022).